NLRP3 (NLR family pyrin domain containing 3)
Diseases named in the same sentence as NLRP3 in open-access papers (continued):
Sharing a sentence is not in itself a finding about the gene and the disease.
viral infection (continued). "NLRP3 plays a dual role in protecting against invading pathogens as well as triggering the cytokine storm that can lead to the development of severe symptoms during viral infection." (PMID 34944639, 2021). "The expression of these innate immune factors, including RIG-I, MAVS and NLRP3, may be up-regulated by viral infections in simple hypertrophic tonsils." (PMID 32487224, 2020). "In this review, we will focus on the crosstalk between the NLRP3 inflammasome and viruses, provide an overview of viral infection-induced NLRP3 inflammasome activation, and the immune escape strategies of viruses through their modulation of the NLRP3 inflammasome activity." (PMID 32133002, 2020). "Viral infection alters the plasma membrane integrity and ionic efflux, which could lead to programmed cell death and induce the secondary activation of NLRP3 inflammasome." (PMID 32133002, 2020). "Pharmacological and genetic inhibition of NLRP3 inflammasomes increased G10-induced type I IFN expression, thereby preventing virus infection, suggesting negative regulation of the NLRP3 inflammasome in the IFN response in the context of STING-mediated innate immune activation." (PMID 33072119, 2020). "Hence, a dysregulation of the NLRP3 inflammasome can also contribute to the utterly complex individual immune response to viral infections." (PMID 33072117, 2020). "Until recently, nothing was known about NLRP3-mediated inflammation in bats, but it was hypothesized that despite the NLRP3 inflammasome existing as a central player in viral infection in bats, it differs between bats and other mammals." (PMID 33363045, 2020). "Obesity is well known to increase the activity of NLRP3 and stimulate low grade inflammation in mice, including higher levels of serum chemokines, and lower neutralizing antibodies and effector memory T cells during a viral infection." (PMID 32470948, 2020). "Here, we established an adult mouse model of Mayaro infection and demonstrated that the virus activates the NLRP3 inflammasome, which is important to regulate this viral disease." (PMID 31479495, 2019). "However, future side-by-side studies are required to elaborate on the relative contribution of NLRP3 activation during different viral infections." (PMID 31572376, 2019). "At 48 h post-infection (hpi), growth media was replaced to remove potential inflammatory cytokines released as a response to the early phase of the virus infection, and NLRP3 inflammasome assembly and activation induced by the classical TLR4 agonist LPS, and ATP." (PMID 31849970, 2019). "Different inflammasomes, including AIM2 and NLRP3, are activated in response to viral infections." (PMID 31479495, 2019). "The NLRP3 inflammasome has been demonstrated to be activated by many RNA viruses and could play distinct roles during viral infections." (PMID 30964929, 2019). "Subsequent studies, however, failed to observe MAVS-dependency of NLRP3 activation by ATP or nigericin, restricting its role to viral infection-associated inflammasome activation." (PMID 31540165, 2019). "Virus infection has been found as an important causative agent of acute kidney injury (AKI), which can be triggered by hyperactivated Nod-like receptor protein 3 (NLRP3) inflammasome." (PMID 31474993, 2019). "A mitochondrial adaptor protein involved in innate immune responses to RNA viruses (see next section) mitochondrial antiviral-signaling protein (MAVS) mediated mitochondrial recruitment and activation of NLRP3 by canonical inflammasome stimuli, e.g. ATP and nigericin, or during viral infection." (PMID 31540165, 2019). "Among the inflammasome-activating sensors, NLRP3 is the most promiscuous, being activated under a variety of conditions, including disruption of ion fluxes, lysosomal membrane damage, and bacterial or viral infection." (PMID 31540165, 2019).
viral infection (continued). "Furthermore, our previous studies indicated that IL-1β, a downstream product of NLRP3 activation, plays an important role in the protection and the pathogenesis of demyelinating disease depending on the level and time after viral infection." (PMID 28445497, 2017). "Both the pathogen-associated molecule pattern derived from virions and intracellular stress molecules involved in the process of viral infection lead to activation of the NLRP3 inflammasome, which in turn triggers inflammatory responses for antiviral defense and tissue healing." (PMID 29163496, 2017). "Indeed, TRIM33 has been shown to regulate NLRP3 inflammasome activation in response to bacterial or viral infection through a direct interaction with DHX33 in the cytoplasm and to regulate Ifnb1 transcription at the late stages of BMDM activation." (PMID 27974684, 2017). "In addition, NLRP3-dependent pyroptosis during RNA viral infection also supports the pathogenesis of virus infection diseases." (PMID 29163496, 2017). "Taken together, our results suggested that NS1 downregulated the NLRP3 inflammasome by targeting NF-κB and NLRP3, which may benefit in vivo virus infection by acting as an immune evasion strategy." (PMID 25978411, 2015). "In addition, NLRP3 is another innate receptor that senses IAV RNAs and requires IPS–1 for optimal activation of NLRP3 complex in response to viral infection." (PMID 26444420, 2015). "By reviewing the research progress made in recent years on the regulation of the NLRP3 inflammasome by viroporins of animal viruses, we aim to understand the importance of viroporins in viral infection and to provide a reference for further research and development of novel antiviral drugs." (PMID 26114475, 2015). "While further studies are required to better understand how RNA viruses exactly activate the NLRP3 inflammasome, our present study indicates that viroporins and disturbances in the intracellular ionic milieu following viral infections are important in RNA virus-induced NLRP3 inflammasome activation." (PMID 22916014, 2012). "Although administration of IL-1β promotes the pathogenesis of TMEV-induced demyelinating disease, the IL-1β produced via NLRP3 proteosome activation upon viral infection is considered to be a protective mechanism against microbial infections by promoting the apoptosis of infected cells." (PMID 22985464, 2012). "Aberrant activation of the NLRP3 inflammasome triggers the release of pro-inflammatory cytokines, including IL-1β, IL-18, and IL-6, potentially leading to a "cytokine storm" in acute inflammatory diseases and viral infections, such as SARS-CoV-2, HSV-1, and influenza." (PMID 39869629, 2025). "Consequently, HERC5-mediated NLRP3 ISGylation in humans and HERC6-mediated ISGylation in mice enhances NLRP3 inflammasome activation, whereas HERC6 deficiency mitigates the NLRP3-dependent inflammation-related pathologies induced by viral infection." (PMID 40307577, 2025). "The exposure of macrophages to LPS constitutes the first of two signals required for the canonical activation of the NLRP3 inflammasome, the second signal being K+ ion efflux from cells initiated by the bacterial toxin nigericin, ROS, or other stress-related stimuli, e.g., virus infection." (PMID 40305196, 2025). "However, the role of NLRP3 in viral infection-induced PANoptosis is enigmatic." (PMID 38932258, 2024). "This suggests that NLRP3 may play a similar regulatory role in different types of viral infections." (PMID 38399989, 2024). "Moreover, future work should address whether melatonin increases Nrf2 to deactivate the NLRP3 inflammasome during a viral infection at the maternal–fetal interface." (PMID 38361952, 2024). "Consequently, in more intricate or advanced disease scenarios, the E protein may mediate a biphasic impact throughout viral infection, characterized by initial immunosuppression followed by the subsequent activation of NLRP3 inflammasomes." (PMID 38399989, 2024).
viral infection (continued). "The NLRP3 is a protein involved in innate immune responses and phosphorylation in this region may modulate interactions with NLRP3, potentially affecting the host’s immune response to the virus infection." (PMID 39653747, 2024). "E protein formed Ca2+ ion channels in ER Golgi apparatus intermediate compartment (ERGIC)/Golgi membranes and impelled reactive oxygen species (ROS)-dependent activation of NLRP3 inflammasome at the later stages of viral infection, which might contribute to advanced or complicated diseases." (PMID 37251383, 2023). "Therefore, the NLRP3 inflammasome is a double-edged sword in host defense against virus infection." (PMID 38249297, 2023). "Furthermore, SARS-CoV-2 infection induces several proinflammatory cytokines such as TNFα, interleukin (IL) -1, and IL-6, and activates the NLR family pyrin domain containing 3 (NLRP3) inflammasome pathway which is important for the host’s defense during viral infection." (PMID 36417106, 2022). "S1PR1 is involved in the regulation of the MAPK and NLRP3 signaling pathways associated with the production of inflammatory factors caused by viral infection, indicating that S1PR1 may regulate inflammatory responses through the MAPK and NLRP3 signaling pathways." (PMID 35854395, 2022). "Thus, the E protein may mediate a biphasic effect during viral infection with initial immunosuppression followed by NLRP3 inflammasome activation in more advanced or complicated disease." (PMID 34952919, 2021). "Molecular mechanisms of lung injury resulting in inflammation and fibrosis are not entirely explained; however, viral infection-associated NLRP3 inflammasomes might have a role in driving lung fibrosis." (PMID 34638790, 2021). "Therefore, the activation levels of NLRP3 upon viral infection are likely to affect the pathogenesis and these results may also help to understand the pathogenesis of MS." (PMID 28445497, 2017). "However, the precise mechanism by which NLRP3 recognizes viral infections remains to be defined." (PMID 22916014, 2012). "Our findings reveal that astrocytes autonomously control SARS-CoV-2 infection via the NLRP3-GSDMD-IL-1β axis, underscoring their active role in the neuroimmune response to viral infection." (PMID 41641274, 2026). "In the area of viral infection, one study suggested that TXNIP activated Epstein-Barr virus (EBV) replication by activating NLRP3 pathway." (PMID 40628121, 2025). "Specifically, spermine has been shown to reduce IL-1β in acute liver injury, suppress NLRP3 inflammasome activation in diabetic atherosclerosis, and downregulate Guanylate Binding Protein 5 (GBP5)-mediated NLRP3 activation during viral infection." (PMID 41463524, 2025). "Caspases, NOD-like receptor family pyrin domain containing three (NLRP3) inflammasomes, and Receptor-Interacting Protein kinases (RIPKs) are essential regulators of PCD, playing key roles in immune responses during viral infections." (PMID 40284946, 2025). "Mammalian ZNFX1 suppresses NLRP3 inflammasome activation in lipopolysaccharide stimulated mice and accelerates the decay of IFN and ISGs mRNA during viral infection, thereby protecting cells from immune storms." (PMID 41160652, 2025). "After virus infection, administration of CLEC5A-blocking antibodies inhibits the NLRP3 inflammasome activation and reduces the release of pro-inflammatory cytokines." (PMID 39443966, 2024). "Here, we report that during PRV infection, ZBP1-mediated NLRP3 inflammasome activation is inhibited by the viral tegument protein VP22, thereby facilitating viral infection." (PMID 39475237, 2024). "Similar with RVFV infection of the Nlrp3-/- mouse model, RVFV-NSsRM infection resulted in reduced fatality rate compared with the WT virus infection and the serum, liver, spleen viral loads were comparable between these two groups." (PMID 39213434, 2024). "ZBP1-mediated PANoptosis was characterized by NLRP3 inflammasome activation with LDH and IL-1β release during viral infection." (PMID 39850894, 2024).
viral infection (continued). "Both NLRP3 and AIM2 have been widely shown to respond to viral infection and significantly contribute to both viral clearance and the induction of severe disease." (PMID 36580480, 2022). "To understand the kinetics of dTGN formation, NLRP3 recruitment, and ASC speck formation after IAV infection, we conducted viral infection and fluorescent microscopy." (PMID 35062292, 2022). "The NLRP3 is the most widely studied and characterized NLR inflammasome, activated during viral infection with highly diverse viruses." (PMID 35806033, 2022). "Here, we reveal the role of the inflammasome components NLRP3 and ASC in this process, thus uncovering a new interplay between effectors of inflammation and viral infection or stress." (PMID 33208442, 2021). "Studies have revealed that NLRP3, AIM2, and IFI16 sensors are pivotal for inflammasome activation in viral infections." (PMID 34595244, 2021). "In the case of viral infection, NF–κB signaling is activated through PRRs–dependent pathways, which induce IFN–β or TNF–α activation that, in turn, activate NF–κB to initiate the NLRP3 inflammasome response." (PMID 34209586, 2021). "During viral infection, DNA or RNA viruses that serves as PAMPs are recognized by a sensor of TLR or NLR results in the transcription and expression of the NLRP3 inflammasome, pro-IL-1β, and pro-IL-18 via NF-κβ upregulation (signal 1 or priming)." (PMID 34638790, 2021). "Several studies have demonstrated that some viruses have the ability to activate diverse inflammasomes, such as the NLRP3, AIM2, and RIG-I inflammasomes, which in turn contributes to mediate the host response to viral infection." (PMID 32324736, 2020). "MAVS recruits TRAF3 to ASC in the context of viral infection, which ubiquitinates ASC promoting its oligomerization, and it therefore enhances NLRP3 inflammasome activation." (PMID 31284572, 2019). "Many viral infections stimulate TLR- or TNF-α-mediated signaling, resulting in the activation of the NLRP3 inflammasome and leading to the subsequent production of IL-1β and COX-2." (PMID 28445497, 2017). "GBP5 promotes NLRP3 (NOD-like receptor protein 3) inflammasome assembly, an inflammasome known to play a critical role in the innate immune response against parasitic, fungal, bacterial, and viral infections 43,44." (PMID 41473269, 2025). "In contrast, group B shows a lower proportion of fully activated NLRP3 inflammasome complexes and a higher proportion of complexes in the priming phase, probably due to lacking the inflammatory stimulus from the viral infection." (PMID 40004007, 2025). "Given that NLRP3 is the most studied inflammasome in viral infections, we investigated whether HSV-2 triggers inflammation through NLRP3 inflammasome activation in THP-1-derived macrophages." (PMID 40510795, 2025). "Furthermore, we observed a positive correlation between the mRNA transcription levels of NLRP3, caspase-1, and GSDMD and the duration of viral infection." (PMID 40284982, 2025). "In addition, we combined viral infection, immunology, biochemistry, cell imaging, and animal approaches to confirm for the first time that HSV-1 infection induced the activation of NLRP3 inflammasome signaling to drive Aβ deposition and AD pathology." (PMID 39026249, 2024). "Thus, in viral infections, Gal3 can interact with TLR4 and regulate the NLRP3 inflammasome, thereby promoting inflammasome assembly and activation, which potentially contributes to enhanced inflammation and tissue damage." (PMID 39125989, 2024). "However, in the NLR family, there are members of great importance for inflammatory functions such as NLRP3 or NLRX1, which regulatory functions on RIG-I/MAVS pathway and are important in viral infection, and NOD2, a less studied effector in viral infections." (PMID 38668261, 2024).
viral infection (continued). "Considering the interaction between NLRP12 and NLRP3, as well as the role of NLRP3 in PANoptosis during viral infections, it can be predicted that PANoptosis orchestrated by NLRP12 plays a role, to varying degrees, in the context of viral infections." (PMID 38932258, 2024). "Our data indicate that 3aCoV2 remodels the TGN in a manner distinct from previously characterized NLRP3 inflammasome stimuli, and as a result, is not a potent NLRP3 stimulus either expressed alone or during viral infection." (PMID 38798602, 2024). "NLRP3 expression is upregulated by acetate once polyI:C stimulation is added, implying that acetate makes the cells faster in inducing NLRP3 expression in response to polyI:C, which potentially promoted IFN-I production quicker when cells encounter viral infections." (PMID 36746963, 2023). "Activation of NLRP3 or other NLR inflammasomes leading to IL-1β/IL-18 secretion and pyroptosis may also have different impact on viral infection and host cell status in different tissues and organs." (PMID 35173184, 2022). "Notably, under the context of viral infection, ECHO 11 effectively induces NLRP3 inflammasome activation in the presence of 2A and 3C." (PMID 36026486, 2022). "Consequently, researchers suggest that FMDV 2B acts as a viroporin during viral infections, and it is also known that the viroporin activity of FMDV 2B mediates NLRP3 inflammasome activation." (PMID 36248821, 2022). "Specifically, MAVS and mitofusin 2 (Mfn2) have been proposed to recruit the NLRP3 protein to mitochondria in response to viral infection or non-mitochondrial NLRP3 activators." (PMID 33807807, 2021). "CASP8 regulates both canonical and noncanonical NLRP3 inflammasome activation in bacterial and viral infections, and it also negatively regulates the necroptotic pathway." (PMID 33109609, 2020). "We next asked whether OM-85 was an effective priming agent for multiple activators of the NLRP3 as well as for the AIM2 inflammasome, as both these platforms are important for detection of and protection from viral infections." (PMID 28262817, 2017). "Although NLRP3 inflammasome plays important role in regulating host immunity and viral infection, the assembly of NLRP3 inflammasome induced by viral infection is not known." (PMID 28060938, 2017). "Conversely, inhibitors targeting caspase-9, pan-caspases, NLRP3 inflammasome, and RIPK1 significantly suppressed NF-κB activation, suggesting that these pathways are involved in the negative regulation of NF-κB activation during IBV infection, as previously suggested for other viral infections." (PMID 40284946, 2025). "However, direct interaction with viral structures is not required for the activation of the NLRP3 inflammasome induced by viral infection, indicating that it has intricate mechanisms for recognizing viruses." (PMID 38932258, 2024). "This suggests that monotherapy to inhibit NLRP3 activity may not provide effective protection against severe viral infection; however, combination therapy may improve overall efficacy in the fight against SARS-CoV-2." (PMID 37515138, 2023). "Finally, we found a positive regulation of genes related to immune response to virus infections (Type I Interferons, inflammatory cytokines (IL-6, TNF and NF-κB), NLRP3 inflammasome, anti-inflammatory cytokines (IL-10), and cell death pathways (pyroptosis and apoptosis)) in RA individuals." (PMID 37628893, 2023). "In addition, NLRP3 and IL-1β expression levels were significantly increased in the mouse model of herpes simplex encephalitis compared with normal mice without viral infection." (PMID 35387080, 2022). "However, it is unclear whether MFN2 is involved in activating the conventional NLRP3 inflammasome complex; whether MFN2 levels affect host defense and pathogenesis during viral infection also remains unclear." (PMID 34482801, 2021).